NOL6 (nucleolar protein 6)
Description:
Part of the small subunit (SSU) processome, first precursor of the small eukaryotic ribosomal subunit. During the assembly of the SSU processome in the nucleolus, many ribosome biogenesis factors, an RNA chaperone and ribosomal proteins associate with the nascent pre-rRNA and work in concert to generate RNA folding, modifications, rearrangements and cleavage as well as targeted degradation of pre-ribosomal RNA by the RNA exosome.
Synonyms: Nrap; bA311H10.1; FLJ21959; MGC14896; MGC14921; MGC20838; UTP22
Tractability: Small molecule: a structure with a bound ligand is known. PROTAC: ubiquitination databases record sites on it; its protein half-life has been measured.
Gene: Protein-coding gene on chromosome 9 (33,461,353 to 33,473,930, reverse strand). Ensembl gene ENSG00000165271.
Subcellular location: Nucleus, nucleolus; Chromosome
Subcellular location (Human Protein Atlas): Nucleoli; Nucleoplasm
Pathways (Reactome):
Metabolism of RNA: Major pathway of rRNA processing in the nucleolus and cytosol; rRNA modification in the nucleus and cytosol
Gene Ontology:
Molecular function: protein binding; RNA binding
Biological process: ribosomal small subunit biogenesis; maturation of SSU-rRNA; rRNA processing; tRNA export from nucleus
Cellular component: nucleolus; nucleoplasm; small-subunit processome; chromosome; condensed nuclear chromosome; CURI complex; UTP-C complex
Genetic constraint (gnomAD): Loss-of-function variants: 33 observed, 129.59 expected, observed/expected ratio (o/e) 0.25, 90% interval 0.19 to 0.34. The upper end of that interval is the gene's LOEUF score, 0.34, which puts it in group 1 of 6, group 1 being the genes least tolerant of losing a copy. Missense variants: 1,296 observed, 1,533.4 expected, observed/expected ratio (o/e) 0.85, 90% interval 0.81 to 0.88. Synonymous variants: 580 observed, 622.82 expected, observed/expected ratio (o/e) 0.93, 90% interval 0.87 to 1.
Homologues: Orthologues: chimpanzee NOL6 (99% identical), macaque NOL6 (97% identical), dog NOL6 (91% identical), pig NOL6 (90% identical), guinea pig NOL6 (88% identical), rat Nol6 (87% identical), mouse Nol6 (85% identical), tropical clawed frog nol6 (58% identical), zebrafish nol6 (53% identical), Drosophila melanogaster Mat89Ba (33% identical), Caenorhabditis elegans nol-6 (24% identical).
Diseases named in the same sentence as NOL6 in open-access papers:
NOL6 is named in the same sentence as 9 diseases in open-access papers, as found by Europe PMC text mining. Sharing a sentence is not in itself a finding about the gene and the disease. The quoted sentences say what the papers report.
prostate carcinoma (3 papers, 2021 to 2022). A carcinoma that arises from epithelial cells of the prostate gland. "Previously, only one study reported an abnormally high expression of NOL6 in prostate cancer, and overexpression of NOL6 promotes proliferation and inhibits apoptosis of prostate cancer cell." (PMID 35494047, 2022). "For example, Nucleolar Protein 6 (NOL6) may have oncogenic functions in endometrial and prostate cancers, while CMTM3 may contribute to proliferation, migration, and poor survival in prostate cancer." (PMID 35624824, 2022).
endometrial cancer (2 papers, 2023). Primary or metastatic malignant neoplasm involving the endometrium (mucous membrane that lines the endometrial cavity). "Other RiBi factors might be of interest as biomarker of efficacy, including NOL6, the human homologous of a yeast snoRNA‐associated protein complex involved in rRNA maturation that has been shown to promote proliferative and migration capacities of endometrial cancer cells." (PMID 36370117, 2023). "Furthermore, NOL6 is overexpressed in endometrial cancer and regulates TWIST1 expression, promotes migration, and reduces apoptosis." (PMID 37667226, 2023).
gastric cancer (2 papers, 2022 to 2023). A primary or metastatic malignant neoplasm involving the stomach. "In summary, we first demonstrated that NOL6 can regulate the oncogenic behaviors of gastric cancer cells by down-regulating TP53I3 and up-regulating CDK4, MCM7." (PMID 35494047, 2022). "Finally, survival analysis showed that the overall survival (OS) of gastric cancer patients with NOL6 overexpression was worse than that of the control group." (PMID 35494047, 2022).
lung carcinoma (1 paper, 2023). "Although PGAM4 and NOL6 have not been actively studied in lung cancer, they are known to promote cell proliferation in other cancers." (PMID 37667226, 2023). "However, further experimental evidence is needed; for example, the roles of PGAM4 and NOL6 have not been studied in lung cancer." (PMID 37667226, 2023).
cancer (4 papers, 2019 to 2023). A tumor composed of atypical neoplastic, often pleomorphic cells that invade other tissues. "PGAM1, PGAM4, and NOL6 have been reported to be tumorigenic in several cancers." (PMID 37667226, 2023).
bacterial infection (3 papers, 2009 to 2021). "Previous studies have shown that RNA interference (RNAi)-mediated knockdown of nol-6, a nucleolar RNA-associated protein, reduces bloating of the intestinal lumen caused by bacterial infection." (PMID 31674907, 2019). "Mutation or silencing of NOL-6 and other nucleolar proteins results in an enhanced resistance to bacterial infections." (PMID 19763173, 2009).
tumor (3 papers, 2019 to 2022). "Results suggested that NOL6 was highly expressed in tumor tissue compare to para-tumor tissue." (PMID 35494047, 2022). "We found that NOP14 interacted with some proteins closely related to tumor initiation and development, such as BYSL or NOL6." (PMID 35473611, 2022). "Additionally, NOL6 knockdown could decrease the weight and volume of tumor in the mice." (PMID 35494047, 2022).
infection (1 paper, 2009). The state of being infected such as from the introduction of a foreign agent such as serum, vaccine, antigenic substance or organism. "Consistent with the idea that the enhanced resistance to pathogen infection of rpa-9 animals is due to a mutation in nol-6, nol-6 RNAi enhances nematode resistance to S. enterica-mediated killing." (PMID 19763173, 2009). "The most highly upregulated gene in rpa-9 or nol-6 RNAi animals was the leucine rich repeat (LRR) encoding gene sym-1, which is one of twelve genes that are signature of C. elegans response to infections by different pathogens, including S. enterica (and Aballay and Tenor unpublished data)." (PMID 19763173, 2009). "Nol-6 RNAi in wild-type nematodes results in a significant decrease in the percentage of nematodes exhibiting intestinal accumulation of S. enterica/GFP 48 hours after the infection." (PMID 19763173, 2009). "The results also show that animals deficient in nol-6 are more resistant to infections by Gram-negative pathogen Pseudomonas aeruginosa and Gram-positive pathogen Enterococcus faecalis, indicating that nucleolar disruption activates immunity against different bacterial pathogens." (PMID 19763173, 2009).
NOL6 also shares sentences with these, for which no sentence is quoted: colorectal cancer (1 paper).